OR4D5 (olfactory receptor family 4 subfamily D member 5)
Description:
Odorant receptor.
Synonyms: OR11-276
Tractability: Antibody: UniProt places it where antibodies can reach, with medium confidence; UniProt predicts a signal peptide or a membrane-spanning region; its Gene Ontology location is reachable by antibodies, with medium confidence.
Gene: Protein-coding gene on chromosome 11 (123,939,617 to 123,940,573, forward strand). Ensembl gene ENSG00000171014.
Subcellular location: Cell membrane
Pathways (Reactome):
Sensory Perception: Expression and translocation of olfactory receptors
Gene Ontology:
Molecular function: olfactory receptor activity; G protein-coupled receptor activity
Biological process: detection of chemical stimulus involved in sensory perception of smell; G protein-coupled receptor signaling pathway
Cellular component: plasma membrane; membrane
Genetic constraint (gnomAD): Missense variants: 379 observed, 397.11 expected, observed/expected ratio (o/e) 0.95, 90% interval 0.88 to 1.04. Synonymous variants: 162 observed, 157.65 expected, observed/expected ratio (o/e) 1.03, 90% interval 0.9 to 1.17.
Homologues: Orthologues: chimpanzee OR4D5 (99% identical), macaque OR4D5 (95% identical), mouse Or4d5 (89% identical), pig OR4D5 (89% identical), rat Or4d5 (89% identical), dog OR4D5 (89% identical). Paralogues in human: OR4D9 (60% identical), OR4D6 (59% identical), OR4D1 (58% identical), OR4D11 (56% identical), OR4D2 (56% identical), OR4D10 (56% identical), OR4N2 (51% identical), OR4N5 (50% identical), OR4C6 (49% identical), OR4Q3 (49% identical), OR4A47 (49% identical), OR4K14 (48% identical), and 116 more.